NLRP3 (NLR family pyrin domain containing 3)
Diseases named in the same sentence as NLRP3 in open-access papers (continued):
Sharing a sentence is not in itself a finding about the gene and the disease.
pulmonary fibrosis (continued). "Nevertheless, our study showed that targeting NOX4-generated ROS and disrupting the self-sustaining cycle between NOX4, ROS, and NLRP3 inflammasomes could effectively inhibit the occurrence and progression of pulmonary fibrosis." (PMID 38166847, 2024). "Research has confirmed that in a silica-induced pulmonary fibrosis model, human umbilical cord MSC-derived extracellular vesicles (HucMSCs-EVs) could transfer miR-223-3p to alleviate pulmonary fibrosis by inhibiting the circPWWP2A/miR-223-3p/NLRP3 axis." (PMID 38071321, 2023). "Since NLRP3 is dispensable in various chronic inflammations, future study designs should consider using these knockout mice to carefully address the role of NLRP3 and caspase-1 in bleomycin-induced pulmonary fibrosis." (PMID 37958797, 2023). "The complete inactivation of the NLRP3 gene could better understand the NLRP3 inflammasome and caspase-1 in the pathogenesis of bleomycin-induced pulmonary fibrosis compared with pharmacological inhibition." (PMID 37958797, 2023). "Furthermore, HIF, mTOR, TGF-β, and NLRP3 play key roles in respiratory diseases such as cancer, pulmonary fibrosis, and cardiovascular diseases." (PMID 37371940, 2023). "The activation of NLRP3 is increased in pulmonary fibrosis, and inhibition of NLRP3 can effectively delay the progression of pulmonary fibrosis, indicating that targeted NLRP3 may be a new choice for the treatment of pulmonary fibrosis." (PMID 36865908, 2023). "To confirm whether the role of SS-31 in NLRP3 inflammasome activation and pulmonary fibrosis was Nrf2 dependent in vivo, we detected the effect of SS-31 on BLM-induced Nrf2−/− mice." (PMID 38136142, 2023). "Considering these facts, we hypothesized that the NLRP3 inflammasome has significant effects on EndoMT in bleomycin-induced pulmonary fibrosis, which could be attenuated by the inhibition of the NLRP3 inflammasome via a reduction in FAK expression." (PMID 37958797, 2023). "ER stress stimulates NLRP3 inflammasome activation and promotes the process of lung fibrosis." (PMID 36865908, 2023). "In addition, the inhibition of the NLRP3 inflammasome via YVAD preventive treatment preserved VE-cadherin levels significantly after bleomycin-induced pulmonary fibrosis." (PMID 37958797, 2023). "Although there are several NLRP3 inhibitors in existence, most of these drugs are still in the pre-clinical phase and there is a lack of validated data to confirm that they are indeed effective in pulmonary fibrosis." (PMID 36865908, 2023). "Immunohistochemistry (IHC) staining of the lung tissues showed that the expression levels of the NLRP3 inflammasome and caspase-1 p20 were significantly higher in the pulmonary fibrosis model group compared to the control group seven days after bleomycin injection." (PMID 37958797, 2023). "In addition to fibroblasts, the NLRP3 inflammasome is also involved in lung fibrosis mediated by alveolar epithelial cells." (PMID 37960237, 2023). "Our study further found that YVAD, a caspase-1 inhibitor, could effectively alleviate bleomycin-induced pulmonary fibrosis both by downregulating the NLRP3 inflammasome and reducing the activity of EndoMT." (PMID 37958797, 2023). "NLRP3 promotes the development of pulmonary fibrosis mainly through the following aspects." (PMID 36865908, 2023). "In BLM—induced mice, Nlrp3−/−, Asc−/−, and Casp1−/− mice exhibited the abrogation of pulmonary inflammation and fibrosis, which highlights the essential role of pyroptosis in the development of pulmonary fibrosis." (PMID 35628193, 2022). "In this study, we explored whether ER stress-induced NLRP3 inflammasome activation promotes type II AECs pyroptosis in a mouse model of bleomycin- (BLM-) induced pulmonary fibrosis." (PMID 36033388, 2022). "Studies have shown that NLRP3 inflammasome is essential for the development of pulmonary fibrosis." (PMID 35628193, 2022). "TiO2 nanowires activated NLRP3 inflammasome in mice during the development of pulmonary fibrosis." (PMID 36364684, 2022).
pulmonary fibrosis (continued). "PM2.5 was found to promote pulmonary fibrosis by activating the NLRP3 inflammasome." (PMID 36248872, 2022). "Furthermore, recent studies have shown that BLM-induced pulmonary fibrosis increases protein levels of NLRP3 inflammasome components, including NLRP3, ASC, and Caspase-1, whereas NLRP3 deficiency results in recovery of lung fibrosis." (PMID 36432032, 2022). "Raltegravir alleviates endoplasmic reticulum (ER) stress and thereby suppresses HIV protease inhibitor-induced inflammation, while simultaneously inhibiting the nucleotide-binding oligomerization domain-like receptor 3 (NLRP3) inflammasome and thus preventing lung fibrosis." (PMID 36350972, 2022). "Interestingly, colocalization of NLRP3 with cAMP also increased in the BLM model group, indicating a potential link between the cAMP/PKA pathway and the NLRP3 inflammasome in type II AECs in BLM-induced pulmonary fibrosis." (PMID 36033388, 2022). "Our observations indicated that upregulation of cAMP/PKA pathway may alleviate pulmonary fibrosis through inhibiting ER stress-induced NLRP3 inflammasome activation in type II AECs." (PMID 36033388, 2022). "Recently, Liang and his colleagues found that an alkaloid “Lycorine” which is isolated from Amaryllidaceae family plants, ameliorated bleomycin-induced pulmonary fibrosis by inhibiting NLRP3 inflammasome activation and pyroptosis via targeting the PYD domain of ASC." (PMID 36248872, 2022). "In addition, previous studies have found that NLRP3 inflammasome promotes epithelial-mesenchymal transition, leading to pulmonary fibrosis." (PMID 36353104, 2022). "Previous findings had reported that silica crystals induce the release of IL-1β and IL-18 and pulmonary interstitial fibrosis through the NLRP3 inflammasomes (tetracycline ameliorates silica-induced pulmonary inflammation and fibrosis via inhibition of caspase-1)." (PMID 36131930, 2022). "Recently, NLRP3 inflammasome has been demonstrated as an important contributor to various fibrotic diseases, following the detection of its constant activation and elevated activation of the Nlrp3 in the lung tissue of both pulmonary fibrosis mice and IPF patients." (PMID 35805187, 2022). "Various studies have shown that activation of the NLRP3/caspase-1 pathway contributes to the inflammatory response through the onset of diseases such as airway inflammation and chronic obstructive pulmonary disease including pulmonary fibrosis." (PMID 34684415, 2021). "Moreover, asbestos and silica, which are known inducers of pulmonary fibrosis, are capable of activating the NLRP3 inflammasome with subsequent IL-1ß production." (PMID 33968032, 2021). "Furthermore, in mice age-dependent mitochondrial dysfunction results in enhanced NLRP3 activation and lung fibrosis." (PMID 34220810, 2021). "Furthermore, exposure to crystalline molecules like asbestos and silica results in pulmonary fibrosis that is regulated by the NLRP3 inflammasome." (PMID 33995030, 2021). "In terms of the toxicology mechanisms involved in rare earth pneumoconiosis, we have demonstrated a NLRP3 inflammasome pathway in macrophage-like cells responsible for REO-induced lung fibrosis by eliciting lysosomal damages, cathepsin B release, and IL-1β release." (PMID 33902647, 2021). "Furthermore, it has been reported that PM2.5 induces lung inflammation and lung fibrosis by activating the NLRP3 inflammasome." (PMID 33419073, 2021). "Additionally, the NLRP3 inflammasome contributes to the development of bleomycin-induced pulmonary fibrosis." (PMID 33419073, 2021). "In addition, previous data have also demonstrated that RES shows protective effects against lung fibrosis by inhibiting NLRP3 inflammasome activation in mice with lipopolysaccharide-induced acute lung injury." (PMID 34123595, 2021). "MiR-21, which is significantly expressed in the lungs of patients with idiopathic pulmonary fibrosis, may also regulate NLRP3 in the case of pulmonary fibrosis." (PMID 34944639, 2021).
pulmonary fibrosis (continued). "Therefore, recent studies suggest that the activation of NLRP3 or AIM2 inflammasome-dependent inflammation has a critical role in the progression of lung fibrosis." (PMID 32121297, 2020). "Nanomaterials induce NLRP3 activation and enhance, therefore the lung fibrosis." (PMID 32508821, 2020). "Metabolic stimulation can also stimulate NLRP3 inflammasome activation in lung fibrosis models." (PMID 32121297, 2020). "NLRP3 participates in the regulation of EMT in bleomycin-induced pulmonary fibrosis." (PMID 32508821, 2020). "Angiotensin (Ang) II has been shown to aggravate lung fibrosis by activating the NLRP3 pathways." (PMID 32724454, 2020). "Thus, we wanted to explore if the activation of NF-κB/NLRP3 signaling was involved in pulmonary fibrosis and if scutellarin regulated this pathway." (PMID 33188176, 2020). "In the present study, we also investigated whether scutellarin regulated EMT process through NF-κB/NLRP3 pathway in BLM-induced pulmonary fibrosis both in vitro and in vivo." (PMID 33188176, 2020). "The latest papers report that attenuating the degradation of NF-κB inhibitor (IκB) could decrease collagen synthesis following silencing of NLRP3 in lung fibrosis." (PMID 30635040, 2019). "The P2RX7 signaling pathway is involved in NLRP3 inflammasome activation, and our data are consistent with the findings of a previous report, in which PHMG-p induced lung fibrosis and pulmonary inflammation through activation of the NLRP3 inflammasome in mouse lung tissue." (PMID 31878359, 2019). "The NLRP3 inflammasome is a key factor that drives the progression of pulmonary fibrosis." (PMID 30087305, 2018). "Therefore, the NLRP3 inflammasome/IL-1β secretion axis is a promising therapeutic target for the prevention and treatment of lung fibrosis." (PMID 29084974, 2017). "The authors demonstrate that vimentin-deficient mice are protected from asbestos- and bleomycin-induced lung injury and fibrosis and that vimentin-expressing bone-marrow-derived cells are important for bleomycin-induced activation of the NLRP3 inflammasome and pulmonary fibrosis." (PMID 27001429, 2016). "In addition to oxidative stress paradigm, recently studies have found Nod-like receptor protein 3 (NLRP3) inflammasome activation plays a major role in PM- and NP-induced chronic effects such as lung fibrosis." (PMID 28649460, 2016). "The activation of NLRP3 inflammosmes results in an inflammatory response mainly driven by the secretion of IL1β, a pro-fibrotic cytokine, playing an essential role in the pathogenesis of inflammation-induced pulmonary fibrosis." (PMID 23110140, 2012). "Mechanistically, UA-mediated NLRP3 inflammasome activation induces IL-1β overproduction, perpetuating pulmonary inflammation through fibroblast-to-myofibroblast transition and extracellular matrix deposition—a pathway corroborated in murine models of silica-induced lung fibrosis." (PMID 40837562, 2025). "However, the effects of FE-induced NLRP3 activation in AT II cells, which may induce a more severe syndrome and contribute to pulmonary fibrosis, remain to be further verified." (PMID 40806699, 2025). "Therefore, the NLRP3 inflammasome not only plays a role in inducing inflammatory responses and promoting the fibrotic process in pulmonary fibrosis, but it may also be an effective target for the treatment of pulmonary fibrosis." (PMID 40391214, 2025). "Thus, using this model, in this study we investigated the effects of NXC736 on the regulation of EMT and pulmonary fibrosis by inhibiting the signaling pathways of NLRP3 and IL-1β in RILF, with the goal of assessing its potential as a pulmonary fibrosis inhibitory drug." (PMID 38003456, 2023). "Similarly, mechanically ventilated mice display less pulmonary fibrosis when NLRP3 is knocked out." (PMID 35743263, 2022).
pulmonary fibrosis (continued). "Thus, we speculated that the negative feedback of the cAMP/PKA pathway regulated ER stress-induced NLRP3 inflammasome activation and pyroptosis in type II AECs which may act as a novel mechanism of pulmonary fibrosis." (PMID 36033388, 2022). "Indeed, previous investigations have also confirmed that NLRP3 inflammasome activation may contribute to disease progression in pulmonary fibrosis." (PMID 36033388, 2022). "It was found that ROS generation induced by silica accelerated pyroptosis in macrophages via the NLRP3/caspase-1 signaling pathway, blocking macrophages’ pyroptosis by inhibiting the NLRP3 inflammasome or caspase-1 could reduce silica-mediated pulmonary fibrosis." (PMID 36248872, 2022). "Thus, we suspected that there might be a similar mechanism in pulmonary fibrosis, such as ER stress facilitating AECs pyroptosis by promoting NLRP3 inflammasome." (PMID 36033388, 2022). "Double-staining showed that the expression of the ER stress marker CHOP and NLRP3 colocalized with surfactant protein C (SPC) in the BLM model group, indicating that ER stress and NLRP3 inflammasome activation were closely linked in type II AECs in BLM-induced pulmonary fibrosis." (PMID 36033388, 2022). "However, it is confused whether ER stress-induced NLRP3 inflammasome activation and pyroptosis in type II alveolar epithelial cells which exacerbates pulmonary fibrosis via a mechanism that is suppressed by cAMP/PKA pathway." (PMID 36033388, 2022). "Therefore, whether ER stress-induced NLRP3 inflammasome activation promotes type II AECs pyroptosis and exacerbates pulmonary fibrosis needs to be established." (PMID 36033388, 2022). "Furthermore, we also investigated whether ER stress upregulated cAMP/PKA pathway and whether upregulation of the cAMP/PKA pathway suppressed ER stress-induced NLRP3 inflammasome activation and pyroptosis in type II AECs which alleviated pulmonary fibrosis." (PMID 36033388, 2022). "Moreover, studies on patients with idiopathic pulmonary fibrosis with long-term hypoxia and accompanying comorbidities demonstrated that pirfenidone suppressed lung inflammation and fibrosis development by blocking the NLRP3 inflammasome." (PMID 34349888, 2021). "Thus, we inferred that scutellarin alleviated BLM-induced inflammation via suppressing canonical NLRP3 inflammasome activation, and we for the first time discovered that scutellarin could suppress inflammation in pulmonary fibrosis by inhibiting NLRP3." (PMID 33188176, 2020). "Nevertheless, the scutellarin treatment dose-dependently reduced the production of inflammatory cytokines IL-1β and IL-18, suggesting that the scutellarin could deliver anti-inflammatory function in pulmonary fibrosis in vitro and NF-κB/NLRP3 pathway might participate in this regulation process." (PMID 33188176, 2020). "Therefore, attenuation of experimental pulmonary fibrosis might be inhibited by NLRP3 activation and highlight its potential use as a novel multitarget drug for IPF." (PMID 31481891, 2019). "However, whether there is a link between mir-21 and the NLRP3 inflammasome in pulmonary fibrosis is unknown." (PMID 29084974, 2017). "Studies have demonstrated that the activated NLRP3 inflammasome can promote pulmonary EMT via the IL-1β/IL-1Rs/MyD88/NF-κB signaling pathway, leading to pulmonary fibrosis." (PMID 40391214, 2025). "Our study confirmed that the activation and accumulation of fibroblasts by NLRP3/IL-1β signaling significantly induced EMT, a key factor in pulmonary fibrosis." (PMID 38003456, 2023). "Previous studies in animal models and patients with pulmonary fibrosis have found that IL-1β and IL-18 levels were significantly elevated in BALF and BALF macrophages, consistent with pre-existing NLRP3 inflammasome activation." (PMID 38136142, 2023). "Higher levels of NLRP3 inflammasome activation were observed in aging AMs in response to BLM, which contributed to the development of BLM-induced pulmonary fibrosis in aged mice." (PMID 36934284, 2023).
pulmonary fibrosis (continued). "Our current study confirmed the potential links among ER stress, NLRP3 inflammasome, and cAMP/PKA pathway in type II AECs in pulmonary fibrosis." (PMID 36033388, 2022). "We found that in vivo, ER stress, NLRP3 inflammasome, and PKA upregulated in the alveolar epithelial area in animal models of pulmonary fibrosis." (PMID 36033388, 2022). "In our research, we explored that potential links among NLRP3 inflammasome, ER stress, and cAMP/PKA pathway in type II AECs to explain the new mechanisms of pulmonary fibrosis." (PMID 36033388, 2022). "This suggests that NecroX-5 ameliorated BLM-induced pulmonary fibrosis by inhibiting the TGF-β1/Smad2/3- mediated EMT process, which is dependent on the inhibition of NLRP3 inflammasomes." (PMID 35596212, 2022). "In this study we provide evidence of an implication of NLRP3 and AIM2 inflammasome in patients with lung fibrosis." (PMID 34220810, 2021). "Immune cells of BALF of patients with idiopathic pulmonary fibrosis (IPF) showed an increased production of IL-1β and hyper-inducible NLRP3 activation." (PMID 34445540, 2021). "By reducing collagen accumulation, pulmonary fibrosis can be effectively improved through TGF-β1 and NLRP3 pathways and decreasing the levels of inflammation factors." (PMID 33013406, 2020). "We further showed that scutellarin inhibited the EMT through regulating NLRP3, which, as far as we known, was the first study that reported the regulatory role of scutellarin on EMT in BLM-induced pulmonary fibrosis." (PMID 33188176, 2020). "The nucleotide-binding oligomerization domain-like receptor 3 (NLRP3) inflammasome and HMGB1/toll-like receptor 4 (TLR4) play vital roles in inflammation and pulmonary fibrosis, and NLRP3 is a key regulator of HMGB1 release." (PMID 31481891, 2019). "Of interest, our longer term (21 day post exposure) aspiration study in mice did observe NLRP3 inflammasome activation (2.4 fold increase in BALF levels of IL-1β) and pulmonary fibrosis in response to La2O3 nanoparticles." (PMID 27527840, 2016). "Inhibition of NLRP3/Caspase-1/GSDMD-mediated pyroptosis largely reversed the injurious effects of hyperoxia, resulting in attenuated lung inflammation, improved alveolarization and pulmonary vascular development, and alleviated pulmonary fibrosis." (PMID 40486518, 2025). "The inhibition of NLRP3-mediated IL-1β production suggests that LA1 could be repurposed to treat NLRP3-mediated inflammatory diseases, such as lung fibrosis." (PMID 40114914, 2025). "Moreover, PM2.5 has been reported to drive inflammatory reactions and promote pulmonary fibrosis through downregulation of PPAR-γ and concurrent activation of the HMGB1/NLRP3 inflammasome pathway." (PMID 41322289, 2025). "In this review, we have synthesised evidence that six exosomal miRNAs, including miR-107, miR-125a-5p, miR-7219-3p, miR-23a-3p, miR-552-3p, and let-7i-5p, critically regulate silicosis-related lung fibrosis by modulating key profibrotic and inflammatory pathways (TGF-β, NF-κB, MAPK, NLRP3)." (PMID 40504442, 2025). "Simultaneously, in vitro pulmonary fibrosis models have shown that ER stress promotes the activation of the cAMP/PKA pathway, which may inhibit the activation of the NLRP3 inflammasome in AECs II induced by ER stress." (PMID 40391214, 2025). "Additionally, NLRP3 activation enhances TGF-β1 secretion, promoting collagen deposition and pulmonary fibrosis." (PMID 40218944, 2025). "The NLRP3 inflammasome and RAS play crucial roles in the pathogenesis of pulmonary fibrosis." (PMID 38762465, 2024). "Our present study suggested that BB might ameliorate BLM-induced pulmonary fibrosis by inhibiting the early inflammatory response, which is probably via the inhibition of the JNK/NF-κB/NLRP3 signal pathway." (PMID 36733844, 2023). "Another research indicated that asbestos and silica could stimulate NLRP3-dominant secretion of IL-1β in THP-1 macrophages, which may trigger pulmonary fibrosis and diseases." (PMID 35415237, 2022).